ZEB2 (zinc finger E-box binding homeobox 2)
Diseases named in the same sentence as ZEB2 in open-access papers (continued):
Sharing a sentence is not in itself a finding about the gene and the disease.
hepatocellular carcinoma (continued). "For example, LncRNA-ATB was shown to induce hepatocellular carcinoma EMT and invasion by competitively binding to and inhibiting miR-200 family members and then upregulating ZEB1 and ZEB2." (PMID 28095858, 2017). "LncRNA-ATB was shown to promote invasion and metastasis in hepatocellular carcinoma through interactions with members of the miR-200 family and with ZEB1/ZEB2." (PMID 28535802, 2017). "For example, lncRNA-ATB was over-expressed in hepatocellular carcinoma and up-regulated ZEB1 and ZEB2 by competitively binding the miR-200, thus inducing invasion." (PMID 27564100, 2016). "In Hepatocellular Carcinoma, lncRNA-activated by TGF-β (lncRNA-ATB) upregulated ZEB1 and ZEB2 by competitively binding the miR-200 family and then induced EMT and invasion." (PMID 27613832, 2016). "However, the expression patterns of ZEB2 in hepatocellular carcinoma (HCC) and its effect on prognosis of HCC patients treated with hepatectomy are unclear." (PMID 22393452, 2012). "In agreement with findings from this study, miR-941 was shown to act as a tumor suppressor by suppressing cancer growth and migration of gastric and hepatoma cells via direct target of EMT inducers SNAIL1, ZEB1 and ZEB2 and promotes E-cadherin expression in the cancer cells." (PMID 33374139, 2020). "Similarly, overexpression of miR-139-5p also inhibits epithelial–mesenchymal transition, migration and invasion of hepatocellular carcinoma cells by targeting ZEB1 and ZEB2." (PMID 29618950, 2018). "Another lncRNA, the lncRNA-activated by TGF-b (lncRNA-ATB) could promote hepatocellular carcinoma (HCC) cell invasion by competitively binding the miR-200 family, upregulating ZEB1 and ZEB2, and then inducing EMT." (PMID 27628540, 2016). "Besides, MALAT1 could bind miR-200s to regulate ZEB2 in ccRCC, while LncRNA-ATB could regulate ZEB1 and ZEB2 by competitively binding the miR-200s to control EMT and invasion in hepatoma cells." (PMID 29156724, 2017). "Though the relationship between ZEB2 and the TGF-β pathway was not clearly clarified in this study, another study on hepatocellular carcinoma complements this part." (PMID 40510028, 2025).
non-small cell lung carcinoma (32 papers, 2014 to 2025). A group of at least three distinct histological types of lung cancer, including non-small cell squamous cell carcinoma, adenocarcinoma, and large cell carcinoma. "LINC00461/miR-30a-5p axis regulates the progression of non-small cell lung cancer by modulating ZEB2." (PMID 34224294, 2021). "lncRNA XIST was found to promote EMT through the regulation of ZEB2 by acting as a miRNA-367/141 ceRNA in non-small cell lung cancer." (PMID 33287341, 2020). "Accordingly, LncRNA Sox2ot can upregulate the expression of zinc finger E-box-binding homeobox 2 (a target of miR-132) via sponging miR-132 and results in triggering the non-small-cell lung cancer tumor cell proliferation and invasion." (PMID 32629426, 2020). "miR-215, as a tumor suppressor, suppresses cell migration and apoptosis in human non-small-cell lung cancer by inhibiting ZEB2." (PMID 32149094, 2020). "For instance, SNHG20 has been demonstrated to promote tumor growth through functioning as a competing endogenous RNA (ceRNA) of miR-154 in non-small cell lung cancer and modulating the expression of ZEB2 and RUNX2." (PMID 32675944, 2020). "In this study, expression levels of miR-200c and miR-9, ZEB-1, ZEB-2 and E-cadherin were assessed in 30 non-small cell lung cancers (NSCLCs) by real-time qPCR." (PMID 31244281, 2019). "The mechanistic effects of miR-132 in EMT were also observed in human non-small cell lung cancer (NSCLC) where ZEB2 was also the major target." (PMID 26784241, 2016). "Notably, several miRNAs suppress migration, invasion, and epithelial-mesenchymal transition in non-small-cell lung cancer through targeting ZEB2." (PMID 40647501, 2025). "miR-215 was reported to be a tumor suppressor in human non-small cell lung cancer by targeting ZEB2 that could be regulated via MAPK/ERK pathway." (PMID 30987362, 2019). "Moreover, GLUT3 expression correlates with both EMT markers (i.e., vimentin, Snail, Slug, ZEB1, ZEB2, Twist1) and glucose uptake in non-small cell lung cancer (NSCLC) cells." (PMID 28352611, 2017). "Another study suggested that hesperidin alleviates non-small cell lung cancer (NSCLC) by suppressing cell proliferation and inducing apoptosis through the miR-132/ZEB2 signaling pathway." (PMID 38998484, 2024). "For example, CASC9 was upregulated in non-small-cell lung carcinoma (NSCLC) and sponged with miR-130b-3p to regulate ZEB2, thus promoted the progression of NSCLC." (PMID 35578597, 2022). "In non-small cell lung cancer (NSCLC), MDM2 binding protein (MTBP) behaves as an oncogene to increase EMT through ZEB2 up-regulation." (PMID 32664703, 2020). "In non-small-cell lung cancer cells, ZEB2 expression was weak regardless of the RAB25 expression level." (PMID 30445998, 2018). "ZEB2/SIP1, as a member of the deltaEF-1 family of two-handed zinc-finger factors, is frequently expressed in a variety of human cancers, including pancreatic, breast, gastric, renal, head and neck, glioma, hepatocellular, ovarian, squamous and non-small cell lung carcinomas." (PMID 24626466, 2014). "Mir-132 directly silences ZEB2, thus attenuating EMT, invasion and metastasis in colorectal and lung cancers, and reduces EMT and migratory/invasive capacity of human non-small cell lung carcinoma (NSCLC) through the EMT-related TGF-β1/Smad2 pathway." (PMID 28792442, 2017).
colon carcinoma (30 papers, 2013 to 2025). "On the contrary, down regulation of ZEB2 is associated with poor prognosis and showed an enhanced potency and invasiveness of colon cancer cells." (PMID 36704357, 2022). "Upregulation of miR-192–5p has also been found to play a role in inhibiting metastatic potential of colon cancer by downregulating expression of Bcl-2, Zeb2 and VEGFA, factors that inhibit apoptosis and promote cell growth." (PMID 40777372, 2025). "It Collaborates with microRNA-155 to regulate the transcription process of Zinc finger E-box binding homology box 2 (ZEB2), inhibiting the expression of ZEB2 in colon cancer." (PMID 38919615, 2024). "The occurrence of colon cancer is closely related to colon polyps and as the expression of ZEB2 decreases, so the possibility of colon polyps occurring also increases." (PMID 36072677, 2022). "LINC01615 competitively binds with miR-3653-3p to regulate ZEB2 and promote the carcinogenesis of colon cancer cells." (PMID 35794984, 2022). "The transcription level of ZEB2 was compared in normal tissues and colon cancer by qPCR and also verified in cancer cell lines and normal cells." (PMID 36072677, 2022). "IEC-specific transgenic expression of the epithelial–mesenchymal transition regulator Zeb2 in mice (Zeb2IEC-Tg/+ mice) leads to increased intestinal permeability and spontaneous invasive colon carcinoma development in a microbiota-dependent manner." (PMID 33262469, 2021). "In colon cancer, vitamin D up-regulates KDM6B and causes the expression of ZEB1, ZEB2, SNAI and other metastasis-related genes." (PMID 34001062, 2021). "B3GALT5-AS1 induces EMT due to the suppression of miR-203 and the subsequent upregulation of miR-203 downstream targets such as ZEB2 and Snail2 in colon cancer cells, leading to colon cancer liver metastasis." (PMID 33246471, 2020). "Further subgroup analyses to evaluate rectal and colon cancer separately found similar findings, and multivariable analysis identified ZEB2 as an independent biomarker (eFigure 4 in the Supplement)." (PMID 30646224, 2018). "Furthermore, RT-PCR was used to detect the expression of ZEB2 in colon cancers and para-cancer tissues, as well as in colon cancer cells and normal cells." (PMID 36072677, 2022). "We can also infer that the expression of ZEB2 is related to the incidence of colon cancer, so the decreased expression of ZEB2 may promote the occurrence of colon cancer." (PMID 36072677, 2022). "In conclusion, our findings showed that ZEB2 was decreased in COAD and strongly correlated with 24 different types of immune cells, therefore ZEB2 may be a potential therapeutic target for colon cancer." (PMID 36072677, 2022). "Interestingly, genes that are associated with colon cancer progression (ANTXR1, EFEMP2, SULF1, TAGLN, VCAN, ZEB1 and ZEB2) were upregulated in patients co-overexpressing TAZ-AXL-CTGF." (PMID 23372686, 2013). "In colon cancer, lncRNA H19 competitively combined with miR-138 and miR-200a, up-regulating the expression of key genes in EMT (VIM, ZEB1, and ZEB2), and promoting the progress of EMT." (PMID 35094653, 2022). "The results displayed that ZEB2 and SNAI2 were both downregulated in liver metastasis tissues compared with primary colon cancer tissues." (PMID 30530918, 2018). "Our data revealed that B3GALT5-AS1 directly binds to the promoter of miR-203, represses miR-203 expression, upregulates miR-203 targets ZEB2 and SNAI2, induces EMT, and finally suppresses colon cancer liver metastasis." (PMID 30530918, 2018). "All these results suggested that B3GALT5-AS1 inhibited miR-203, upregulated ZEB2 and SNAI2, induced EMT, and suppressed colon cancer liver metastasis in vivo." (PMID 30530918, 2018). "In this study by using publicly available microarray datasets, we for the first time showed a negative correlation between EVI1 and all the known EMT related transcription factors (SNAIL, SLUG, ZEB1, ZEB2, TWIST1, and TWIST2) in colon cancer patient samples." (PMID 29339729, 2018).
colon carcinoma (continued). "In addition, the regulation of Zeb2 by miR-192 may reduce metastasis in colon cancer." (PMID 26287603, 2015). "Interestingly, ZEB1 has been shown to be a downstream target of TAZ in retinal pigment epithelial cells, suggesting that ZEB1 may act as a downstream effector of TAZ to promote cancer metastasis, while ZEB1 and ZEB2 have also been shown to be prognostic markers in colon cancer." (PMID 23372686, 2013). "ZEB2 is differentially expressed in tumors and can regulate the growth of tumor cells but the specific role of ZEB2 in colon cancer has not been explored in depth." (PMID 36072677, 2022). "Conversely, miR-192 suppresses the ZEB2 and VEGFA expressions in colon cancer cells." (PMID 31590680, 2019). "Moreover, individual markers that indicate or drive EMT in colon cancer showed a significant overexpression in tumors with high RBP7 expression, including ZEB1 (r = 0.27, P < 0.0001) and ZEB2 (r = 0.36, P < 0.0001)." (PMID 31598160, 2019). "In addition, the expressions of ZEB2 and SNAI2 were measured in the same 15 pairs of primary colon cancer tissues and corresponding liver metastasis tissues." (PMID 30530918, 2018). "Genistein reversed the EMT of colon cancer cells by upregulation of E-cadherin and downregulation of N-cadherin, accompanied by the suppression of EMT related makers, such as Snail2/slug, ZEB1, ZEB2, FOXC1, FOXC2 and TWIST1." (PMID 29202800, 2017). "miR-192-5p decreased the liver metastasis of colon cancer in an orthotopic mouse model of colon cancer through targeting the expression of several oncogenic genes, including anti-apoptotic BCL2, Wnt/β-catenin activator called zinc finger E-box binding homeobox 2 (ZEB2) and pro-angiogenic VEGFA." (PMID 32610706, 2020).
pancreatic cancer (29 papers, 2010 to 2026). "This cadherin switch was also associated with increased Twist, Snail, Zeb1, and Zeb2 expression, findings that are reminiscent of those observed in pancreatic cancer cells under hypoxic conditions." (PMID 21887310, 2011). "Our study found that ZEB1 is overexpressed at both the mRNA and protein levels in pancreatic cancer tissue, whereas ZEB2 was characterized by lower mRNA and higher protein levels." (PMID 41481650, 2026). "Under the effect of ceRNA regulation, cascades ADAM12, MET, QKI, SEC23A, and ZEB2 were reported as PDAC disease signatures that significantly impacted the survival rates of pancreatic cancer patients." (PMID 40728965, 2025). "miR-200c-5p, for instance, is a well-characterized suppressor of ZEB1/ZEB2, and its downregulation is associated with EMT activation in pancreatic cancer." (PMID 40728965, 2025). "The suppression of lncRNA reduced the levels of ZEB2, a regulatory protein involved in the induction of invasion in pancreatic cancer." (PMID 37245177, 2023). "ZEB2 is expressed in several tumours, including metastatic ovarian and breast carcinoma, pancreatic cancer, oral squamous cell carcinomas, gastric cancer, bladder cancer and glioma." (PMID 36499447, 2022). "Spectacularly, miR-215 inhibits ZEB2 expression by directly targeting effects on ZEB2 and pancreatic cancer cell proliferation, invasion, and migration." (PMID 32149094, 2020). "ZEB2 expression was reduced by miR-181b mimics transfection in SW1990 and PANC-1 cells and the mRNA expression level of ZEB2 was higher in pancreatic tumor tissues than that in the paired adjacent ones." (PMID 30250401, 2018). "Here we found that the expression level of ZEB2 in pancreatic cancer tissues was higher than that in the paired adjacent ones." (PMID 30250401, 2018). "Hypoxic pancreatic cancer cells exhibited substantial upregulation of Twist, Snail, Zeb1, and Zeb2 as compared with normoxic cells." (PMID 21887310, 2011). "It is likely that ZEB2 also plays a role in EMT of pancreatic carcinoma cells, for ZEB2 mRNA levels inversely correlate with the expression of E-cadherin and increase with advanced tumor stages." (PMID 24281218, 2010). "The comparison of EMT-TFs expression levels between PDAC and healthy pancreatic tissue revealed significantly elevated mRNA levels of SNAI1, SNAI2, ZEB1 and TWIST in pancreatic cancer tissue, while ZEB2 expression was higher in normal pancreatic tissue (p < 0.05)." (PMID 41481650, 2026). "Additionally, NEAT1 drives chemoresistance to gemcitabine in pancreatic cancer (PC) cells by regulating ZEB2 expression through the miR-506-3p/ZEB2/EMT axis." (PMID 40248198, 2025). "Furthermore, over-expression of Notch-1 has been found led to the acquisition of EMT phenotype by up-regulation of mesenchymal cell markers, ZEB1, ZEB2, Snail2, and down-regulation of epithelial cell marker, E-cadherin, in pancreatic cancer cells." (PMID 29202800, 2017). "As shown, in pancreatic cancer tissues MXRA5 is co-expressed with a number of key ECM-TFs, including Zeb1, Zeb2, Twist and Slug." (PMID 36828810, 2023). "In pancreatic cancer, FoxM1 is overexpressed and promotes EMT by the up-regulation of mesenchymal cell markers, such as ZEB1, ZEB2, SLUG and vimentin." (PMID 36499447, 2022). "In pancreatic cancer, DLX6-AS1 has been found to up-regulate the expression of Zinc finger E-box-binding homeobox 2 (ZEB2) by sponging miR-181b and then promote cancer cell proliferation and invasion." (PMID 32785606, 2020). "We demonstrated that DLX6-AS1 up-regulated the expression of Zinc finger E-box-binding homeobox 2 (ZEB2) by sponging miR-181b, therefore promoting cell proliferation, invasion as well as epithelial-mesenchymal transition in pancreatic cancer cells." (PMID 30250401, 2018).
pancreatic cancer (continued). "E-cadherin (CDH1 gene) is suppressed in several cancer types including pancreatic cancer by its repressors ZEB1 (zinc finger E-box-binding homeobox 1) and SIP1 (Smad-interacting protein 1, ZEB2, and SMADIP1) which thus act as EMT-activators." (PMID 25960741, 2015). "We also observed a subsequent reduction of miR-200 downstream targets ZEB1 and ZEB2, SNAIL and SLUG following the knockdown of DCLK1 in pancreatic tumor xenografts." (PMID 24040120, 2013). "Other studies have previously identified Zeb1, Zeb2, and Snail as central regulators of E-cadherin suppression and EMT in pancreatic cancer cells." (PMID 21887310, 2011). "Finally, SPINT1 knockdown in the pancreatic cancer cell line SUIT-2, induced EMT and invasion which were accompanied by ZEB2 elevation and CDH1 reduction." (PMID 21747944, 2011). "In addition, a negative correlation between miR-181b and ZEB2 mRNA expression in pancreatic cancer tissues was observed." (PMID 30250401, 2018).
leukemia (18 papers, 2015 to 2025). A malignant (clonal) hematologic disorder, involving hematopoietic stem cells and characterized by the presence of primitive or atypical myeloid or lymphoid cells in the bone marrow and the blood. "Several proximal super-enhancers were found to be located at leukemia-associated genes such as GATA2, STAT5A/B, and ZEB2, as expected of super-enhancers found in a leukemia cell line." (PMID 28526829, 2017). "Furthermore, the shRNA-mediated knockdown of Zeb2 in mice MLL-AF9 AML cells caused a reduction in the leukemia cell proliferation." (PMID 39941895, 2025). "Furthermore, ZEB2 was identified as an essential transcription factor for leukemia cell stemness maintenance, and loss of ZEB2 led to aberrant differentiation and decreased proliferation." (PMID 29685144, 2018). "Consistently, we observed multiple peaks in the upstream region of TREM2 in a ZEB2 ChIP-seq profile of K562 leukemia-derived cells." (PMID 41300781, 2025). "High expression of ARID2, JMJD1C, MBNL1, MEF2C, or RUNX2 alone is associated with at least one indicator of poor prognosis in ALL patients, and CPEB2, MBNL1, RUNX2, and ZEB2 are all specifically overexpressed in MLL-FP leukemias." (PMID 28076791, 2017). "Extended survival of the transplanted NOD/SCID in the A7R34-treated animals was seen, indicating that enhanced Il7r levels and its downstream signalling is contributing to the increased leukaemia-initiating capacity of the Zeb2-overexpressing tumours." (PMID 25565005, 2015). "In line with a presumed ETP-ALL phenotype for the mouse Zeb2-driven leukaemias, we also observed increased LSC properties." (PMID 25565005, 2015). "The knockdown of ZEB2 led to the delay in leukemia progression." (PMID 39941895, 2025). "Here, we show a similar phenomenon for Zeb2 deletion in enhancing survival in MLL-AF9 leukemia." (PMID 34550965, 2021). "The model has been successfully used to confirm the role of Zeb2 in leukemia growth." (PMID 33327558, 2020). "Although ZEB2 is best known for its role in repressing E-cadherin and promoting epithelial–mesenchymal transition (EMT), recent studies have associated its aberrant expression in AML and ETP-ALL with gross maturational arrest and an aggressive poorly differentiated stem-cell-like leukemia." (PMID 36229595, 2022). "Thus, we hypothesized Zeb2 is critical for AE leukemia maintenance and/or progression and used the platform to test this hypothesis." (PMID 33327558, 2020). "The ability of EMT transcription factors to alter LSD1 function is an emerging theme in AML and other leukemias such as ETP-ALL, as ZEB2 has previously been demonstrated to interact with LSD1 in both of these settings." (PMID 39200378, 2024). "We tested the platform by inducing knockdown of Zeb2, a gene upregulated by AML1-ETO and PML-RARα oncogenes in pre-leukemic hematopoietic stem cell compartment, and observed a significant delay in leukemia onset." (PMID 33327558, 2020). "Interestingly, there was no additional delay in the progression of leukemia observed when both Zeb1 and Zeb2 from the MLL-AF9 model were knocked out." (PMID 39941895, 2025). "Indeed, several of the IRF8/MEF2D direct target genes, such as MYC, HOXA9, and ZEB2, are highly expressed and essential in non-KMT2Ar leukemias and normal hematopoietic progenitors that do not express high levels of IRF8/MEF2D." (PMID 35301220, 2022). "Interestingly, RUNX2, MBNL1, JMJD1C, SENP6, MEF2C, and ZEB2 are also hypomethylated in MLL-FP samples compared to either normal cells or other leukemias (not shown)." (PMID 28076791, 2017).